MTOR (mechanistic target of rapamycin kinase)
Diseases named in the same sentence as MTOR in open-access papers (continued):
Sharing a sentence is not in itself a finding about the gene and the disease.
liver fibrosis (continued). "Our findings were in agreement with the results of previous studies that ATRA inhibited mTOR activation in myeloid leukemia cells and liver fibrosis, while another study demonstrated that ATRA enhanced mTOR activity in adipose-derived stromal cells." (PMID 31143119, 2019). "Inhibition of mesenchymal mTOR overactivation and the induction of myofibroblasts present potential treatments for liver fibrosis." (PMID 27819329, 2016). "In the experimental hepatic fibrosis model, after liver cell injury, mTOR pathway activation in mesenchymal cell enhanced the wound healing response." (PMID 27819329, 2016). "In summary, mTOR overactivation in the mesenchymal compartment augmented liver fibrosis induced by CCl4." (PMID 27819329, 2016). "It was also observed that plumbagin sharply inhibited other signals, such as pSTAT3, NF-κB/p65, and Akt/mTOR in LX-2 cells, which all are involved in inflammation and liver fibrosis." (PMID 27756878, 2016). "Our data further indicated that the mTOR signaling pathway was activated in CCl4− mediated liver fibrosis, which is consistent with a previous study that reported mTOR activation in liver fibrosis in an animal model." (PMID 27819329, 2016). "Based on the therapeutic action of rapamycin, these data implied that AKT/mTOR singnaling did play a vital role in the formation of hepatic fibrosis and portal hypertension induced by BDL from another perspective." (PMID 24404143, 2014). "To gauge the impact of targeting mTOR pathway on liver fibrosis and portal hypertension induced by BDL, we treated BDL rats with the mTOR inhibitor rapamycin for two weeks." (PMID 24404143, 2014). "Rapamycin can depress EMT induced by transforming growth factor-β, inhibit rabbit liver fibrosis, and reduce the kidney and peritoneal damage in the rat remnant kidney model by inhibiting the mTOR signaling pathway." (PMID 22219636, 2011). "Moreover, isoliquiritigenin exerts protective effects against MASH and liver fibrosis by inducing autophagy through modulation of the PI3K/AKT/mTOR pathway." (PMID 41601875, 2026). "Therefore, inhibiting the activation and proliferation of HSCs and inducing apoptosis of activated HSCs by targeting the PI3K/Akt/mTOR signaling pathway has become one of the main strategies for treating liver fibrosis." (PMID 39388703, 2025). "Clinically, our results suggest that targeting the PI3K/Akt/mTOR pathway with natural products like Huangqi Decoction may offer a safe and effective alternative or complementary therapy for patients suffering from hepatic fibrosis." (PMID 39388703, 2025). "Subsequent research has indicated that anti-PCSK9 treatment may hold the potential to mitigate liver fibrosis by modulating the AMPK/mTOR/ULK1 signaling pathway, thus reducing hypoxia-induced autophagy in hepatocytes." (PMID 39090671, 2024). "This confirmed that the PI3K/AKT/mTOR pathway was activated in the mouse model of liver fibrosis." (PMID 39359922, 2024). "The activation of the PI3K/Akt/mTOR signaling pathway by curcumin can effectively inhibit autophagy, suppress the activity, and induce apoptosis in LX-2 cells derived from the HSCs line, thereby attenuating the progression of liver fibrosis." (PMID 39175576, 2024). "However, it has been shown that combined administration of taurine, EGCG and trihydroxyflavone (genistein) can reduce p-AMPK protein expression and increase p-mTOR protein expression and anti-liver fibrosis." (PMID 38202710, 2023). "Additionally, it was found that membrane-bound glycoprotein CD73 promoted activation and autophagy of HSCs by promoting AMPK/AKT/mTOR signaling pathway, which was conducive to alcohol-related liver fibrosis." (PMID 37539053, 2023). "Recent data highlighted that salvianolic acid A, a traditional Chinese medicine extracted from Danshen, may curtail the process of liver fibrosis by regulating the PI3K/AKT/mTOR signaling pathway." (PMID 36777627, 2023).
liver fibrosis (continued). "Further investigation is required to determine whether it is clinically feasible to prevent liver fibrosis by pharmacologically inhibiting the PI3K/AKT/mTOR signaling pathway." (PMID 37724132, 2023). "Finally, the mechanism of Ufl1/Ufbp1-mediated liver fibrosis regulation was investigated and the interaction between the Ufl1/Ufbp1 and mTOR/GβL complexes was confirmed." (PMID 37131258, 2023). "Meanwhile, they also confirmed that CAPE may attenuate liver fibrosis by inhibiting AKT/mTOR signaling pathway." (PMID 33609264, 2021). "Activation of mTOR signal pathway plays important roles in liver diseases, and mTOR inhibitor rapamycin could ameliorate liver fibrosis, autoimmune hepatitis through regulation Th17/Treg cell balance." (PMID 33510172, 2021). "Potential regulation of exosome secretion by mTOR signaling pathway has emerged as a novel research field in liver fibrosis, however, whether it inhibits or induces secretion remains controversial." (PMID 35185602, 2021). "Our study showed that TDF, which was originally an antiviral drug, was associated with the inhibition of p-PI3K, p-Akt and p-mTOR expression, which led to the downregulation of Bcl-xl and consequently HSC apoptosis to ameliorate liver fibrosis both in vitro and in vivo." (PMID 34879114, 2021). "In addition, another recent study reported that lncRNA GAS5 plays the role of sponge for miR-23a to repress hepatic fibrosis via the PI3K/Akt/mTOR pathway and upregulation of Snail in the CCl4-induced rat model." (PMID 32413995, 2020). "In addition, it has been reported that Asiatic acid can ameliorate CCl4-induced liver fibrosis in rats by regulating PI3K/AKT/mTOR, Bcl-2/Bax, Nrf2/ARE, NF-κB/IκBα and JAK1/STAT3 signaling pathways." (PMID 31467589, 2019). "Previous studies have shown mTOR signaling is activated during liver fibrosis." (PMID 27819329, 2016). "We specifically focused on the role of mesenchymal mTOR overactivation in liver fibrosis." (PMID 27819329, 2016). "Based on the findings of these studies, we speculate that activation of mTOR signaling in mesenchymal cells might also play a role in liver fibrosis." (PMID 27819329, 2016). "In addition, the PI3K/AKT/mTOR pathway also plays an important role in keloids and liver fibrosis." (PMID 38179473, 2024). "We then asked whether mTOR signaling regulates γδ T cell function in CCl4-induced liver fibrosis." (PMID 35361750, 2022). "Conversely, nano-selenium supplements could reduce or prevent the development of liver fibrosis, and the possible mechanism is that the mTOR signaling pathway regulates the down-regulation of mitophagy to avoid the damaging effects of abnormally activated mitophagy on the liver." (PMID 35745140, 2022). "However, overexpression of miR-101 completely reversed this, so downregulating the PI3K/Akt/mTOR signaling pathway may be feasible against hepatic fibrosis." (PMID 34381815, 2021). "In addition, using AZD5363 (an AKT inhibitor that activates autophagy) and AZD8055 (an mTOR inhibitor, another autophagy activator), we further verified that RvD1 suppressed autophagy-mediated HSC activation and alleviated CCl4 induced liver fibrosis partly through AKT/mTOR pathway." (PMID 34987404, 2021). "After obtaining evidence supporting our hypothesis that mTOR overactivation was involved in the process of liver fibrosis, we further demonstrated that mTOR activation resulting in increased myofibroblast accumulation in the liver could be a major mechanism underlying fibrosis formation." (PMID 27819329, 2016). "We hypothesized that AKT/mTOR signaling pathway was activated in the pathophysiological onset of early cirrhotic portal hypertension, and rapamycin treatment would have multiple mechanisms of action against hepatic fibrosis and portal hypertension progression." (PMID 24404143, 2014).
liver fibrosis (continued). "The ubiquitinated TIM3 then bound with PI3K and followed by inhibition of mTOR and activation of macrophage M2 polarization and TGF-β release, leading to HSC activation and liver fibrosis." (PMID 40251185, 2025). "We concluded that alpha-pinene reduced CCl4-induced liver fibrosis by lowering oxidative stress, suppressing liver inflammation, and inhibiting TLR4/NF-κB, TGF-β/Smad3, and PI3K/Akt/mTOR signaling pathways." (PMID 39968080, 2025). "In experimental models of hepatic fibrosis, downregulation of PI3K/AKT/mTOR signaling coincided with autophagy activation and HSC activation." (PMID 40391189, 2025). "AKT and mTOR, which are pivotal components of the PI3K pathway, have the potential to regulate the activation of HSC and the progression of liver fibrosis." (PMID 39698464, 2024). "In conclusion, this is the first evidence that PB can effectively alleviate liver fibrosis in TGF-β1-stimulated LX-2 cells by suppressing autophagy and promoting apoptosis via the mTOR-dependent pathway." (PMID 38257331, 2024). "Ufl1 and Ufbp1 play critical roles in preventing liver fibrosis, steatohepatitis, and HCC by acting as inhibitors of the mTOR pathway, highlighting their potential as therapeutic targets for liver diseases." (PMID 39247188, 2024). "In a rat model of CCL4-induced liver fibrosis, miR-23a induces liver fibrosis through the PTEN/PI3K/Akt/mTOR/snail signaling pathway, while lncRNA-GAS5 acts as a ceRNA to decrease miR-23a expression and suppressing liver fibrosis." (PMID 39044218, 2024). "After administering different doses of CHLD to rats with carbon tetrachloride-induced hepatic fibrosis, the protein phosphorylation levels of PI3K, Akt, mTOR, and mRNA expression levels of corresponding genes in their tissues were increased to varying degrees." (PMID 39239653, 2024). "During liver fibrosis, some signaling pathways and elements of these pathways are overactivated or inhibited, such as TGF-β/Smad and AMPK/mTOR." (PMID 38202710, 2023). "Our results demonstrated that hADMSCs-Exo ameliorated hepatic fibrosis mainly by restoring the abnormal choline metabolism and inhibiting PI3K/Akt/mTOR Pathway." (PMID 36698192, 2023). "By modifying or inhibiting the PI3K/AKT/mTOR pathway, various potential inhibitors, such as some natural compounds, offer the ability to prevent HSC activation and liver fibrosis." (PMID 37724132, 2023). "AKT and mTOR, key molecules of the PI3K pathway, can inhibit the activation of HSC and liver fibrosis." (PMID 37083803, 2023). "Dietary polyphenols are used in the treatment of liver fibrosis and act through multiple pathways, such as TGF-β/Smad, AMPK/mTOR, Wnt/β-catenin, NF-κB, PI3K/AKT/mTOR, hedgehog pathways and liver fibrosis-related factors." (PMID 38202710, 2023). "In conclusion, TA significantly alleviates liver fibrosis in vivo by inhibiting the glycerophospholipid metabolism pathway and the PI3K/Akt/mTOR and NF-κB signaling pathways." (PMID 35359829, 2022). "For example, paeoniflorin inhibits HIF-1α translation by mTOR and attenuates CCL4-induced liver fibrosis in rats." (PMID 35682354, 2022). "The initiation of phosphorylation of PI3K, AKT, and even mTOR in the PI3K/AKT signaling pathway can trigger the activation and proliferation of HSC and affect the production of liver fibrosis." (PMID 35529927, 2022). "The main molecular signaling pathway by which autophagy exerts its multifunctional role during liver fibrosis is through Phosphoinositide 3-kinase/Protein kinase B (PKB), also known as Akt/mammalian Target of Rapamycin (PI3K/Akt/mTOR)." (PMID 35185602, 2021). "More recently published studies have demonstrated correlation between PI3K/Akt/mTOR activity and occurrence and development of NAFLD and liver fibrosis." (PMID 33658028, 2021). "This drug reduced experimental kidney as well as liver fibrosis and was found to block hepatic stellate cell activation via modulation of intracellular ATP levels and the LKB1/AMPK/mTOR pathway." (PMID 32316235, 2020).
liver fibrosis (continued). "The decrease of p-mTOR and p-AKT level was detected in dimethylnitrosamine (DMN)-induced hepatic fibrosis model after treatment of dioscin." (PMID 32948162, 2020). "Several important signaling pathways, such as mTOR/HIF-1α, TGF-β1/Smads, and JAK2/STAT6, are involved in the effect of paeoniflorin on activated HSC and ECM inhibition during liver fibrosis." (PMID 32410996, 2020). "Recently, Hu found that Sestrin 2 can inhibit liver fibrosis by inhibiting rat HSCs activation and proliferation through an AMPK/mTOR-dependent mechanism." (PMID 31835352, 2019). "Paeoniflorin, as one typical TCM was tested in liver fibrosis and proved to affect HIF-1α through mTOR-dependent pathway." (PMID 31105564, 2019). "Studies have also shown that hUC-MSCs and their exosomes alleviate lipid deposition and liver fibrosis in MASH mice through mechanisms involving the upregulation of Etoposide-Induced gene 24 (EI24) protein and AMPK/mTOR signaling as well as activation of autophagy." (PMID 40129979, 2025). "Luteolin, as found in many identified peaks (8, 37, 38, 39 & 41), was reported to suppress the progression of liver fibrosis in four animal models induced by CCl4, DMN, BDL, and thioacetamide directing AKT/mTOR/p70S6K, PI3K/Akt pathways and TGFβ/Smad signaling pathways." (PMID 40892759, 2025). "Studies have shown that blocking the PI3K/Akt/mTOR signaling pathway can reduce the adhesion and migration abilities of HSCs, inhibit their proliferation, and reduce the synthesis of ECM collagen, thereby affecting the development of liver fibrosis." (PMID 39388703, 2025). "The mammalian target of rapamycin (mTOR), a critical regulator of autophagy and a downstream effector of the PI3K/AKT pathway, is known to negatively regulate autophagy and plays a significant role in the pathogenesis of liver fibrosis." (PMID 40391189, 2025). "Furthermore, liver fibrosis can be mitigated through AMPK phosphorylation and inhibition of mTOR-dependent signaling cascades." (PMID 39698464, 2024). "This indicates that CHLD can regulate the mRNA and protein expression of genes related to the PI3K/Akt/mTOR pathway, affecting the expression of autophagy marker proteins LC3 and p62, preventing the activation of hepatic stellate cells, and inhibiting liver fibrosis." (PMID 39239653, 2024). "In previous studies on liver fibrosis, researchers found that the activation of the PI3K/AKT/mTOR pathway may be one of the mechanisms contributing to the onset and progression of hepatic fibrosis." (PMID 39359922, 2024). "Ufl1 and Ufbp1 prevent liver fibrosis, steatohepatitis, and HCC by inhibition of mTOR." (PMID 39247188, 2024). "In contrast to CCl4-induced liver fibrosis, this study found that the degree of p-mTOR protein in the model band did not change significantly, and in some cases even decreased." (PMID 39359922, 2024). "Considering core targets of the PPI network and a network of the common targets and pathways enriched, AKT1, MAPK1, EGFR, MTOR, and SRC may be the core potential targets of CL against hepatic fibrosis." (PMID 37478207, 2023). "Furthermore, REDD1 is involved in autophagy via mTOR signaling, and the knockdown of SHP2 increases REDD1 expression, reduces the expression of α-SMA induced by CCl4 in mice, and attenuates liver fibrosis." (PMID 37654036, 2023). "Considering the main targets showed by PPI network, we speculate that AKT1, MAPK1, EGFR, MTOR, and SRC may be the core potential targets of CL against hepatic fibrosis, and molecular docking was further performed." (PMID 37478207, 2023). "Moreover, choline supplementation cooperated with hADMSCs-Exo in anti-hepatic fibrosis and inhibited PI3K/AKT/mTOR pathway." (PMID 36698192, 2023).
liver fibrosis (continued). "Consistent with the results of previous animal studies, the investigation of the cell insulin signaling pathway suggested that the H-L + HFD-induced liver fibrosis was mediated by gut microbiota through disruption of the gut barrier TLR4/MYD88 and liver IRS1/Akt/mTOR signaling pathways." (PMID 36204709, 2022). "TA treatment significantly ameliorates CCl4-induced liver fibrosis, which may be attributed to the inhibition of the glycerophospholipid metabolism pathway and the PI3K/Akt/mTOR and NF-κB signaling pathways." (PMID 35359829, 2022). "Although there are discrepancies regarding the role of autophagy as a promoter or inhibitor of liver fibrosis, there are several lines of evidence that PI3K/Akt/mTOR pathway is a major molecular mechanism that is regulated from upstream signals such as growth factors, energy status, oxygen levels." (PMID 35185602, 2021). "In addition, paeoniflorin imposes strong inhibition effect on mTOR-hypoxia inducible factor-1a pathway, leading to a reduction of alpha-smooth muscle actin (a-SMA) and collagen protein production and alleviation of liver fibrosis." (PMID 33240030, 2020). "Consequently, the lncRNA GAS5/miR-23a/PTEN/PI3K/Akt/mTOR/Snail and GAS5/miR-222/p27 signalling pathways can provide molecular targets for the treatment of liver fibrosis." (PMID 32098245, 2020). "Moreover, a number of mTOR inhibitors have been reported to inhibit HSC proliferation and attenuate hepatic fibrosis in vivo and in vitro." (PMID 31263154, 2019). "However, in hepatic fibrosis, ICA can exert an anti-autophagic effect by restoring mTOR expression." (PMID 40535758, 2025). "In addition, blocking mTOR and phosphorylating AMPK ameliorates liver fibrosis." (PMID 38202710, 2023). "Therefore, PKSH may inhibit the activation of HSC by inhibiting the key molecules AKT and mTOR in the PI3K/AKT signaling pathway, thus inhibiting liver fibrosis." (PMID 37083803, 2023). "Therefore, it may be possible that TDF downregulates adenosine and A2AR levels, which results in the inhibition of PI3K/Akt/mTOR phosphorylation and ultimately leads to HSC apoptosis and the amelioration of liver fibrosis." (PMID 34879114, 2021). "Therefore, it is possible that PI3K/Akt/mTOR pathway may play a critical role in the development of NAFLD and liver fibrosis." (PMID 33658028, 2021). "Besides, mTOR inhibitor Rapamycin and PI3K inhibitors LY294002 were employed in LPS-treated HSC-T6 cell cultures to verify that Rg3 partially reversed the increase in autophagy in hepatic fibrosis in vitro." (PMID 32532964, 2020). "In CCl4-induced hepatic fibrosis in mice without treatment, the level of mTOR phosphorylation was elevated and participated in hepatic fibrogenesis, followed by high-expressed p-p70S6K, while luteolin ameliorates liver fibrosis via suppressing AKT/mTOR/p70S6K signaling pathway." (PMID 28638431, 2017). "To date, the specific effect of mTOR on liver fibrosis has not yet been reported." (PMID 27819329, 2016). "However, the potential role of mTOR in γδ T cells during liver fibrosis is not well characterized." (PMID 35361750, 2022). "In addition, miR-193 plays a protective role in pulmonary and hepatic fibrosis by regulating canonical TGF-β/SMAD2/3 and non-canonical TGF-β/PI3K/AKT/mTOR signaling pathways, respectively." (PMID 34381815, 2021).